IFNG (interferon gamma)
Diseases named in the same sentence as IFNG in open-access papers (continued):
Sharing a sentence is not in itself a finding about the gene and the disease.
infection (continued). "The finding that the RNA polymerase III pathway partially contributed to the inhibitory effect of IFNγ on S. flexneri suggests that S. flexneri DNA accesses the cytoplasm and is involved in the IFNγ-mediated immune response during infection." (PMID 22912573, 2012). "From experimental studies increases in IFNγ secreting cells and interleukin 10 have been shown as early as 7 and 10 days post infection, respectively." (PMID 22439879, 2012). "Primary mouse macrophages or rat L2 fibroblasts pre-treated with IFNγ prior to infection significantly inhibit S. flexneri growth compared to untreated cells." (PMID 22912573, 2012). "NK cells and NKT cells secrete IFNγ and are thought to limit exponential growth of the bacteria primarily by activating macrophages during the first few days of infection." (PMID 22912878, 2012). "In our study, we have found an increase of spleen CD4+ T lymphocytes producing IL-10 seven days after infection, in addition to the IFNγ and TNF-α producing cells." (PMID 22666132, 2012). "IFNγ–producing CD4+ T cells were already detected at d14 of infection in both the liver and spleen of WT mice, although still at low frequency." (PMID 21253574, 2011). "Conversely, infection for 4 hr markedly reduced the extent of IFNγR2 coprecipitation with IFNγR1 even in IFNγ stimulated condition, while the level of coprecipitated IFNγR2 went below detection level with increasing time of infection." (PMID 21931549, 2011). "It was recently shown that IFNγ-secreting CD4 T cells are necessary for the migration of herpes simplex virus-specific CD8 T cells to the site of infection." (PMID 21901102, 2011). "T cells rely on IL-12 to differentiate into a Th1 phenotype and produce IFNγ at the site of infection." (PMID 21931790, 2011). "Interferon gamma (IFNγ) is another critical immunomodulator in early host defense against a variety of infections." (PMID 21887255, 2011). "Infection of mice with T. gondii elicits a dominant Th1 response involving interferon-gamma (IFN-γ), interleukin-12 (IL-12), IL-18, and tumor necrosis factor alpha (TNF-α)." (PMID 21957440, 2011). "A recent study demonstrated that infection of mice with lymphocytic choriomeningitis virus reprogrammed otherwise stably committed Th2 cells to adopt an IL-4+IFNγ+ “Th2+1” phenotype that was maintained in vivo for months." (PMID 21533073, 2011). "During Ft infection, IFNγ-positive NK cells are quickly recruited to sites of infection, where they promote granuloma formation and limit bacterial spread." (PMID 22072975, 2011). "Reflected in this is the fact that infection by members of this subgenus generates a hyperinflammatory and mixed Th1/Th2 response (and high levels of IFNγ) that can fail to resolve." (PMID 21695103, 2011). "IFNγ is a key activator of macrophage killing activity and also recruits circulating neutrophils and lymphocytes to the sites of infection." (PMID 21887255, 2011). "IFNγ and interleukin-2 (IL-2) responses following in vitro re-stimulation were measured by flow-cytometry prior to, during and more than one year post infection." (PMID 22144890, 2011). "Nude mice as well as IFNγ−/− mice infected with 5×104 Tulahuen dhfr-ts+/− parasites succumbed after 20–25 days of infection even though the parasite load in these infected mice was significantly lower than with Tulahuen wild type parasites." (PMID 22180798, 2011). "We also found increased serum levels of IFNγ persisting through infection in mice pre-treated with L1S polypeptide." (PMID 22072975, 2011). "In the mouse, infection promotes myelopoiesis, a process that is critically dependent on interferon gamma (IFNγ) signaling." (PMID 22194881, 2011). "This represented a significant and highly selective lipogenic response with altered genes showing a high degree of overlap between infection and IFNγ activation." (PMID 21408089, 2011).
infection (continued). "As this was found to be low in infected cells (E = 0.166 in 4 hr and E = 0.042 in 12 hr LD infection) compared to that (E = 0.465) of normal IFNγ stimulated condition, LD infection must have significantly inhibited ligand induced receptor association." (PMID 21931549, 2011). "Measurements of cytokines in the BALF obtained from mice at 24 and 48 hours post-infection indicated that the levels of IFNγ were drastically reduced in Il-18-/- mice, a finding consistent with the established function of IL-18 as an IFNγ-inducing cytokine." (PMID 22241982, 2011). "Both Interferon gamma (IFNγ) (primarily from NK cells) and tumor necrosis factor alpha (TNFα) are essential for early resistance to infection." (PMID 21559416, 2011). "As infection progresses, an adaptive immune response develops with production of high levels of inflammatory cytokines, IFNγ and NO radicals." (PMID 21909255, 2011). "At 16 weeks post-infection, unvaccinated animals exhibited a marked up-regulation in the levels of IFNγ and TNFα in comparison to 10 weeks post-infection." (PMID 21533158, 2011). "Seven days after infection, the cells from the infection control group (S) increased significantly (p < 0.01) the release of IFNγ and TNFα, compared to the untreated control (C)." (PMID 21813005, 2011). "We have established a model in which infection with an interferon-gamma-producing C. neoformans strain, H99γ, elicits protective host immunity against pulmonary cryptococcosis in mice." (PMID 21359196, 2011). "IFNγ activates the microbicidal activity of macrophages and has been shown to be important for resistance against infection with many pathogens including B. pseudomallei." (PMID 22241982, 2011). "On the other hand, activated T cells recruited to the site of infection help epithelial cells to clear viruses through production of IFNγ and TNF, and induction of epithelial NOS2 expression." (PMID 22022590, 2011). "Infection by Listeria monocytogenes (Lm) rapidly activates a large population of NK cells to produce IFNγ." (PMID 22072975, 2011). "Cell-mediated immunity, measured as virus-specific interferon-gamma (IFN-γ) secreting cells (SC), has an erratic behaviour for several weeks after the onset of infection showing afterwards a trend to increase and reach a steady state." (PMID 21314968, 2011). "FL8-specific CTL demonstrated a strong IFNγ response with an average magnitude of 46–101 SFUs at 96 hours post-infection against endogenously presented FL8 peptide by cells infected with clade A isolates HIV-192UG029 and HIV-192RW024 respectively." (PMID 21589893, 2011). "Kinetically, CD8 T-cell production of IFNγ begins 2-3 days after parasite infection with eventual contraction out to 21 days after infection followed by low numbers being maintained." (PMID 21687650, 2011). "On one hand, it is required for host resistance as shown in studies using Ifnγ−/− mice; on the other hand, excess IFNγ production during infection leads to host damage leading in turn, to increased susceptibility to C. albicans." (PMID 22114559, 2011). "IFNγ levels were significantly higher (p < 0.01) in mice administered continuously with the probiotic (Lc-S-Lc) compared to the infection control group (S) for 7 and 10 days post challenge." (PMID 21813005, 2011). "In these experiments the early clearance of the infection is solely dependent on IFNγ secreted by the transferred NR1 cells, since the recipient mice are deficient for IFNγ production." (PMID 21731484, 2011). "Our data support a model whereby infection-induced IFNγ acts on normally quiescent HSCs to undergo transient activation, in order to promote an expedited innate immune response." (PMID 22194881, 2011). "IFNγ expression is induced by infection with E. muris, and IFNγ signaling is required for protection against E. muris infection." (PMID 22194881, 2011). "At 10 weeks post-infection BCG vaccinated animals exhibited very low levels of all the cytokines studied (IFNγ, TNFα, TGFβ, IL10 and IL12)." (PMID 21533158, 2011).
infection (continued). "The cooperative nature of the strategy is evident by the lack of IFNAR1-dependent inhibition of ISREΔ replication we observe late in acute infection, which correlates with increased lethality in a moderately immune compromised (IFNγ-/-) host." (PMID 22114555, 2011). "While the spleen stays chronically infected, infection in the liver is self-resolving within 6-8 weeks due to the development of a Th1-dominated granulomatous response, which is characterized by high IFNγ production." (PMID 21253574, 2011). "It is worth noting, however, that the observed level of reduction in expression for any particular transcript was relatively modest (ranging from 1.3- to 5-fold for infection and 1.3- to 3-fold for IFNγ treatment over a 24 h time frame)." (PMID 21408089, 2011). "Nevertheless, the release of IFNγ from these cell cultures was significantly higher in the infection control (S) than in the mice given probiotic (Lc-S-Lc group)." (PMID 21813005, 2011). "During infection, expression of inflammatory cytokines, such as IFNγ, can modulate the expression of cell surface proteins used to identify stem and progenitor cells." (PMID 22194881, 2011). "The transfer of purified LCMV-immune CD4+ T cells to CD8-depleted mice largely restored the relative and absolute number of LCMV-specific CD4+ T cells producing IFNγ at day 8 and 11 after infection." (PMID 21966366, 2011). "Our results show, however, that in the absence of the relevant TLRs, i.e. TLR2 and TLR4, CD4+ T-cells can be sensitized to release IFNγ upon infection with C. pneumoniae." (PMID 22096480, 2011). "CD8+ T cell depletion resulted in a drastic reduction of the relative and absolute number of LCMV-specific CD4+ T cells producing IFNγ and TNFα on day 8 and 11 after infection." (PMID 21966366, 2011). "In accordance with the CD107a levels, 3h following infection the IFNγ transcript level in the lungs was significantly higher in Ncr1+/gfp mice compared to Ncr1gfp/gfp infected mice." (PMID 21887255, 2011). "IFNγ levels peaked during the first week of infection and most notably on day 3 p.i. that showed the highest levels of IFNγ (p = 0.007)." (PMID 21835036, 2011). "Serological and interferon gamma release assays (IGRAs) in these patients show suboptimal sensitivity and cannot differentiate between disease and infection." (PMID 21283655, 2011). "The infection-induced changes were accompanied by an expansion of more differentiated multipotent progenitor cells, and required IFNγ signaling." (PMID 22194881, 2011). "Proinflammatory cytokines IL-1β and TNFα were augmented by the C. parapsilosis-infected oral epithelial cells at early and late infection periods, while IFNγ was involved only at early defense phase, as previously reported with C. albicans." (PMID 20454633, 2010). "In the periphery, infection rapidly induces IFNγ, which in turn induces the IRG protein response in lymphoid and other cells." (PMID 20664789, 2010). "It was reported that the presence of IFNγ during the first 2 days after sublethal intradermal infection ensures survival." (PMID 20585449, 2010). "The upregulation of TLRs was paralleled by an increase of IL-1β, TNFα, and IFNγ mRNA expression, suggesting the involvement of these cytokines in the defense against infection with C. parapsilosis." (PMID 20454633, 2010). "In cattle, a more complex Th1/Th2-mixed cytokine pattern involving production of IFNγ and IL-4 has been reported during infection with Ostertagia ostertagi." (PMID 20356390, 2010). "The infection of hepatic DCs restored their capacity to stimulate allogeneic T-cell proliferation and to induce lymphocytic secretion of IFNγ." (PMID 20544029, 2010). "The infection of these DCs with L. donovani amplified their Th2 polarizing cytokine profile and restored their ability to stimulate the proliferation and IFNγ secretion of T lymphocytes." (PMID 20544029, 2010).
infection (continued). "The in vivo contribution of IFNγ to the protection from LVS was clearly demonstrated in gamma interferon knockout (GKO) mice, which were highly susceptible to LVS infection via all routes." (PMID 20585449, 2010). "After infection of IFNγ-induced cells with avirulent T. gondii, five out of the six IRG proteins studied were found in high density on the PVM." (PMID 20109161, 2010). "Neutralization of IFNγ by antibodies concomitantly to intradermal sublethal infection resulted in death of the mice (wild type, nude or SCID strains) within a week." (PMID 20585449, 2010). "For the macrophages data the BGM model inferred a biologically plausible state change in the host macrophage brought about by infection (CMV) or immune activation (IFNγ), and a less pronounced state change in the combined condition CMV+IFNγ." (PMID 20721277, 2010). "Both NADPH oxidase and IFNγ were required to control SL1344 atp infection with bacterial counts in livers and spleens significantly higher in the absence of these host defence mechanisms." (PMID 19925904, 2010). "In vitro infection of CD4+-T cells with HIV also results in downregulation of IFNγ expression, while commencement of HIV-infected patients on antiretroviral therapy leads to an increase in IFNγ production." (PMID 21048923, 2010). "To be sure that IL-2Jc did not stimulate NK cells or NKT cells, we examined their expression of the activation markers CD69, GzmB and IFNγ, 24 hours after infection and treatment with IL-2Jc." (PMID 21170302, 2010). "When PD-L expression on CD11c+ cells was blocked ex vivo, their ability to restimulate allogenic CD4+ T cells to produce IFNγ was restored to the level observed during acute infection." (PMID 20625513, 2010). "For instance, neutrophils, TNFα and IFNγ are far more important for controlling primary versus secondary LVS infection." (PMID 20967278, 2010). "Then, it is possible that IL-10 and/or IFNγ, which increase during infection, as well as TLR ligands expressed by T. cruzi or parasite antigens trigger BAFF secretion." (PMID 20454564, 2010). "Lung-residing natural killer (NK) cells have been shown to become activated and to secrete IFNγ following intransal infection with LVS." (PMID 20585449, 2010). "The inflammatory cytokines IFNγ and IL-6 are concomitantly produced in the lungs following infection as well." (PMID 20585449, 2010). "By day 7 of infection, levels of IFNγ (90–250-fold), IL-6 (360–390-fold), IL-17 (30–75-fold), KC (20–35-fold), TNFα (5–13-fold), and IL-2 (2–3.5 fold) were significantly elevated above background in all three vaccinated groups." (PMID 20967278, 2010). "In fact, when we compared experimental lagochilascariosis in C57BL/6 and BALB/c mice, the latter were more resistant to infection and produced more IFNγ and IL-10." (PMID 20721343, 2010). "Faced with the persistance of P46 overexpressing L. major in C57BL/6 mice, we tested cytokine production in draining lymph nodes 17 days post infection, using IL-4 and IFNγ sandwich ELISA." (PMID 20345655, 2010). "The level of IFNγ in serum increased drastically after giving single infection with 107 CFU of WT Salmonella as compared to the vaccine strain." (PMID 20161765, 2010). "Infection, for example by mycobacteria, induces a high level of IFNγ, which in turn induces high levels of IRG proteins." (PMID 20664789, 2010). "Nevertheless, we provide evidence of a critical role of UNC93B1 in mediating IL-12 as well as early IFNγ production during acute infection with T. gondii." (PMID 20865117, 2010). "We focused here on the early encounter of macrophages with Mtb and included IFNγ to model the influence of NK cells and γδ T cells that produce IFNγ during the earliest days of infection, as do early-arising αβ T cells." (PMID 21170273, 2010). "It has been reported that many decades after infection, relatively high frequencies of gI-specific interferon gamma were detected ex-vivo and are dominated by CD4+ T cells." (PMID 23675158, 2009).
infection (continued). "Does infection of hepatocytes induce IFNβ or do resident endothelial cells, Kupffer cells, or infiltrating lymphocytes release IFNα/β or IFNγ in response to HCV replication?" (PMID 19688046, 2009). "To determine if defective IFNγ signaling in IFN-γR−/− mice was associated with high levels of Twist, we analyzed expression levels of Twist by IHC at 15 days post-infection in lungs of C57BL/6 infected mice." (PMID 19851501, 2009). "In contrast, post-infection Ag85A specific IFNγ responses were relatively low (in the sub-nanogram range), and on average lower in non-vaccinated controls than in BCG/MVA and SO2 vaccine groups particularly." (PMID 19367339, 2009). "IFNγ was also detected in response to PVM infection in both wild type and in IFNγR-/- mice, albeit at higher levels among the latter group, most likely due to the absence of feedback inhibition (data not shown)." (PMID 19298652, 2009). "Initial analyses of a complex data set comprised of relevant immune soluble and cellular factors indicated that IFNγ differed significantly among cats with single and dual infections at some time points." (PMID 19806226, 2009). "Specific immune responses in the post-infection phase were monitored by measuring IFNγ secretion levels from fresh PBMC samples stimulated in vitro with PPD, recombinant Ag85A or ESAT6/CFP10 fusion protein." (PMID 19367339, 2009). "We evaluated Th1 cell immunity in immunized mice after vaginal challenge by quantitating the number of CD3+CD4+ cells that secrete IFNγ or IL-4 in iliac lymph nodes (ILNs) during peak infection (day 7) and during resolution of infection (day 15)." (PMID 19404403, 2009). "For both post-vaccination (pre-infection) and post-infection timepoints coefficients of correlation between individual maximal antigen specfic IFNγ levels and total PA lesion scores were calculated." (PMID 19367339, 2009). "Lymphocyte stimulation revealed Ag85A-induced IFNγ levels post-infection as the strongest immunocorrelate for protection (spearman's rho: −0.60)." (PMID 19367339, 2009). "This sequence of events occurs on a large scale only following infection of IFNγ-induced cells with an avirulent strain of T. gondii, and is reduced by expression of a dominant negative mutant IRG protein." (PMID 19197351, 2009). "Interferon-gamma release assays (IGRAs) using specific M. tuberculosis antigens provide an alternative to tuberculin skin testing (TST) for infection detection." (PMID 20011589, 2009). "Evidently, the complement of highly expressed IRG proteins would normalize in hepatocytes as soon as the IFNγ levels begin to rise during infection, and we show that IFNg-induced primary hepatocytes are able to control T. gondii replication." (PMID 20368812, 2009). "The cellular response against a TK-negative strain of HSV-2 led to viral control in an intravaginal model of infection in an IFNγ-dependent manner." (PMID 21994578, 2009). "VZV-specific IFNγ responses were higher in patients with mild infection (median 622 spot forming units/million cells) than in patients with moderate/severe disease (median 40 spot forming units/million cells)." (PMID 19023425, 2008). "In these immune mice, approximately 5% of all CD8+ T cells had made IFNγ within 12 hours of re-infection with LCMV, recapitulating published data from this laboratory, and others." (PMID 18404208, 2008). "The inflammatory gene profiles showed up-regulation during infection of eight genes, including IFNG and IL12A, which indicated an antiviral response." (PMID 18398488, 2008). "Further, we showed that all hitherto identified members of the mGBP family are IFNγ induced and moreover are highly upregulated in mice after infection with L. monocytogenes or T. gondii." (PMID 18402675, 2008).